GPS1 (G protein pathway suppressor 1)
Description:
Essential component of the COP9 signalosome complex (CSN), a complex involved in various cellular and developmental processes. The CSN complex is an essential regulator of the ubiquitin (Ubl) conjugation pathway by mediating the deneddylation of the cullin subunits of SCF-type E3 ligase complexes, leading to decrease the Ubl ligase activity of SCF-type complexes such as SCF, CSA or DDB2. Suppresses G protein- and mitogen-activated protein kinase-mediated signal transduction.
Synonyms: SGN1; COPS1; CSN1
Tractability: PROTAC: ubiquitination databases record sites on it; its protein half-life has been measured.
Gene: Protein-coding gene on chromosome 17 (82,050,691 to 82,058,057, forward strand). Ensembl gene ENSG00000169727.
Subcellular location: Cytoplasm; Nucleus
Subcellular location (Human Protein Atlas): Nucleoplasm; Cytosol
Pathways (Reactome):
DNA Repair: DNA Damage Recognition in GG-NER; Formation of TC-NER Pre-Incision Complex
Metabolism of proteins: Neddylation
Signal Transduction: RHOBTB1 GTPase cycle
Vesicle-mediated transport: Cargo recognition for clathrin-mediated endocytosis
Gene Ontology:
Molecular function: protein binding; GTPase inhibitor activity
Biological process: protein deneddylation; JNK cascade; protein neddylation; regulation of protein neddylation
Cellular component: COP9 signalosome; cytoplasm; cytosol; nucleoplasm; nucleus
Genetic constraint (gnomAD): Loss-of-function variants: 11 observed, 53.98 expected, observed/expected ratio (o/e) 0.2, 90% interval 0.13 to 0.34. The synonymous counts are far from expectation, so gnomAD's model fits this gene poorly and the ratio says little. Missense variants: 543 observed, 635.77 expected, observed/expected ratio (o/e) 0.85, 90% interval 0.8 to 0.92. Synonymous variants: 343 observed, 259.61 expected, observed/expected ratio (o/e) 1.32, 90% interval 1.21 to 1.45.
Homologues: Orthologues: macaque GPS1 (99% identical), chimpanzee GPS1 (98% identical), dog GPS1 (98% identical), guinea pig GPS1 (98% identical), rat Gps1 (97% identical), pig GPS1 (96% identical), mouse Gps1 (96% identical), zebrafish gps1 (92% identical), tropical clawed frog gps1 (92% identical), Drosophila melanogaster CSN1b (64% identical), Caenorhabditis elegans csn-1 (29% identical). Paralogues in human: PSMD6 (18% identical).
Diseases named in the same sentence as GPS1 in open-access papers:
GPS1 is named in the same sentence as 20 diseases in open-access papers, as found by Europe PMC text mining. Sharing a sentence is not in itself a finding about the gene and the disease. The quoted sentences say what the papers report.
virus infection (2 papers, 2013 to 2019). "First, to confirm that GPS1 plays a role in virus transcription and translation, viral protein expression levels were assessed in the context of the virus infection." (PMID 31848286, 2019). "Further unveiling of the functions of GPS1 may lead to the discovery of an antiviral drug that is effective against a variety of viral infections." (PMID 31848286, 2019).
asthenozoospermia (1 paper, 2020). "Subsequent Sanger sequencing on genomic DNA from all the available family members (III:1, III:2, and IV:1–7) verified four variants in four genes (DNAH17, GPS1, HID1, and USP36) recessively coinherited with asthenozoospermia." (PMID 31658987, 2020).
breast carcinoma (1 paper, 2024). "In the TISIDB database, GPS1 was significantly associated with immunological subtypes in breast cancer patients (p < 0.001)." (PMID 38289496, 2024). "Further, we analyzed the predictive value of GPS1 as a diagnostic indicator in the diagnosis of breast cancer and its staging." (PMID 38289496, 2024). "Based on the bioinformatics analysis and in vitro experimental studies, we concluded that GPS1 may be a potential diagnostic biomarker for breast cancer, which is closely related to immune cell infiltration, cell proliferation, migration and invasion of breast cancer." (PMID 38289496, 2024). "To further investigate the biological function of GPS1 in breast cancer, we characterized the co-expressed genes and related pathways of GPS1." (PMID 38289496, 2024). "High expression of GPS1 in different pathologic grades of breast cancer suggests poor prognosis, and this difference is particularly significant in low- and intermediate-grade breast cancers." (PMID 38289496, 2024). "Analysis of the proteomics data further confirmed that GPS1 can be involved in the development of breast cancer through multiple pathophysiological processes." (PMID 38289496, 2024). "In this study, we performed a comprehensive bioinformatics analysis to investigate the expression profile, prognostic value, biological function, and potential regulatory pathways of GPS1 in breast cancer." (PMID 38289496, 2024). "The biological function of GPS1 in breast cancer cell lines MCF7 and MDA-MB-231 was studied by down-regulating the expression of GPS1 by siRNA in vitro." (PMID 38289496, 2024). "Further, we also analyzed the relationship between methylation and prognosis of breast cancer, we analyzed the effect of GPS1 methylation status on the prognosis of breast cancer using the GEPIA database." (PMID 38289496, 2024). "The results of this study showed that the expression of GPS1 in Luminal B and Basal type breast cancer was significantly higher than that in Luminal A type (p < 0.05)." (PMID 38289496, 2024). "The bioinformatics analysis and basic research in this paper will help to better understand the role of GPS1 in breast cancer and provide a reference for future research." (PMID 38289496, 2024). "Survival analyses indicated that patients with high GPS1 expression made the prognosis worse in Luminal B, low to intermediate-grade breast cancers." (PMID 38289496, 2024). "Kaplan–Meier Plotter database was used to evaluate the impact of GPS1 on the prognosis of breast cancer in terms of the four main subtypes of breast cancer, the presence or absence of lymph node metastasis, and pathologic grading." (PMID 38289496, 2024). "The results showed that in breast cancer, GPS1 expression was positively correlated with LAG3, PVRL2, and LGALS9, and negatively correlated with CD274 and HAVCR2, but not with CTLA4 and PDCD1." (PMID 38289496, 2024). "In breast cancer, although GPS1 has been shown to be associated with WBP2-mediated activation of the Wnt signaling pathway, its specific molecular regulatory mechanism in breast cancer is unclear." (PMID 38289496, 2024). "Finally, in vitro experimental studies revealed that knockdown of GPS1 significantly inhibited the proliferation, migration and invasion ability of breast cancer cells." (PMID 38289496, 2024).
breast carcinoma (continued). "As an immunotherapeutic target currently under investigation, the correlation between LAG3 and GPS1 may provide new ideas for effective immunotherapy of breast cancer." (PMID 38289496, 2024). "Therefore, in this paper, we assessed the correlation between GPS1 expression and immune inhibitors in breast cancer through the TISIDB database." (PMID 38289496, 2024). "The receiver operating curve (ROC) revealed that GPS1 had some accuracy in predicting breast cancer (AUC = 0.832) and could be used as an adjunctive diagnosis of breast cancer, but was less accurate in determining breast cancer staging (AUC < 0.7)." (PMID 38289496, 2024). "In addition, we evaluated the effects of GPS1 on breast cancer cell migration and invasion." (PMID 38289496, 2024). "Therefore, we hypothesized that GPS1 could regulate tumor immune cell infiltration to influence breast cancer development." (PMID 38289496, 2024). "Studies have shown that in the breast cancer cell line MDA-MB-231, WBP2 initiates cellular Wnt activity through the upregulation of GPS1 and TNIK." (PMID 38289496, 2024). "To elucidate the role of GPS1 in breast cancer progression, we investigated the biological function of GPS1 in MCF7 and MDA-MB-231 cells by knocking down the expression of GPS1 by siRNA." (PMID 38289496, 2024). "Notably, WBP2, a gene co-expressed at position 68 of GPS1, is an emerging oncogene that has received recent attention for its oncogenic role in TNBC breast cancers." (PMID 38289496, 2024). "G protein pathway suppressor 1 (GPS1) is involved in the development of many diseases including tumors, but its specific regulatory mechanism in breast cancer is not clear." (PMID 38289496, 2024). "The results showed that the prognostic value of GPS1 was significant in Luminal B breast cancer, and the prognosis was worse in those with high expression of GPS1 (p < 0.01), whereas no significant prognostic significance was found in Luminal A, Basal-like, and HER2 + breast cancers." (PMID 38289496, 2024).
esophageal squamous cell carcinoma (1 paper, 2025). Esophageal squamous cell carcinoma (ESCC) is a type of esophageal carcinoma (EC) that can affect any part of the esophagus, but is usually located in the upper or middle third. "Previous research has shown that BNC1 serves as a key transcriptional activator in esophageal squamous cell carcinoma and that LINC01305 recruits BNC1 to act on G-protein pathway suppressor 1 to promote tumor progression." (PMID 40444282, 2025).
gastric adenocarcinoma (1 paper, 2023). "In addition, our data show for the first time that GPS1 is associated with the progression of gastric adenocarcinoma." (PMID 36520032, 2023).
hepatocellular carcinoma (1 paper, 2023). A malignant tumor that arises from hepatocytes. "In hepatocellular carcinoma cells, GPS1 promotes cell proliferation and migration by upregulating the expression of cyclin A2." (PMID 36520032, 2023).
lymph node metastasis (1 paper, 2024). "High expression of GPS1 in patients was significantly negatively correlated with prognosis, and the difference was significant only in the group without lymph node metastasis." (PMID 38289496, 2024).
Moyamoya disease (1 paper, 2013). Moyamoya disease (MMD) is a rare intracranial arteriopathy involving progressive stenosis of the cerebral vasculature located at the base of the brain causing transient ischemic attacks or strokes. "Using the novel functional interpolating single-nucleotide polymorphisms bioinformatics approach, we identified 6 Moyamoya Disease-associated autoantibodies against APP, GPS1, STRA13, CTNNB1, ROR1 and EDIL3." (PMID 23518061, 2013).
multiple sclerosis (1 paper, 2014). A progressive autoimmune disorder affecting the central nervous system resulting in demyelination. "Gene Ontology enrichment analysis revealed that TNFSF10 involved in the biological processes including protein kinase cascades, regulation of signal transduction and apoptosis, and the GPS1 and TRPS1 were primarily enriched in multiple sclerosis." (PMID 24932510, 2014).
Newcastle disease (1 paper, 2022). A condition caused by infection by the Newcastle disease virus, which may be characterized by conjunctivitis, respiratory illness, and diarrhea. "Our results show that GPS-1 can effectively amplify the immune response to Newcastle disease vaccination, cytokine secretion ability, and the development of immune organs in Lohmann Brown chickens." (PMID 36090181, 2022). "GPS-1, Glycyrrhiza polysaccharide extract 1; ND, Newcastle disease; NDV, Newcastle disease vaccine; PHA-P, Phytin; mGM-CSF, Chicken recombinant proteins GM-CSF; il-4, Interleukin 4; chBM-DCs, immature chicken bone marrow dendritic cells." (PMID 36090181, 2022).
pancreatic cancer (1 paper, 2015). "However, there is no reported role for GPS1 in pancreatic cancer at present." (PMID 25929337, 2015).
cancer (3 papers, 2014 to 2024). A tumor composed of atypical neoplastic, often pleomorphic cells that invade other tissues. "The expression status of GPS1 in pan-cancer was estimated using the TIMER database." (PMID 38289496, 2024). "The results showed that GPS1 was highly expressed in most cancers, such as BLCA, BRCA, CHOL, ESCA, LIHC, and was lowly expressed in a few cancers, such as KICH, KIRC, and THCA." (PMID 38289496, 2024).
infection (2 papers, 2007 to 2019). The state of being infected such as from the introduction of a foreign agent such as serum, vaccine, antigenic substance or organism. "While cluster 7 showed a set of genes involved in cell cycle (P29, APBB2, GPS1) and the TGFβ-pathway (BMPR2, THBD) up-regulated 6 hours post infection, no concise network or significant functions/pathways could be identified." (PMID 18047719, 2007).
GPS1 also shares sentences with these, for which no sentence is quoted: tumor (4 papers); Penile Squamous Cell Carcinoma (2); glioma (1); lung diseases (1); Obesity (1); prostate carcinoma (1); triple-negative breast carcinoma (1).